ANKRD20A3P (ankyrin repeat domain 20 family member A3, pseudogene)
Synonyms: formerly ANKRD20A3
Gene: Transcribed unprocessed pseudogene on chromosome 9 (66,083,960 to 66,152,966, reverse strand). Ensembl gene ENSG00000276203.
Genetic constraint (gnomAD): Loss-of-function variants: 1 observed, 1.93 expected, observed/expected ratio (o/e) 0.52, 90% interval 0.17 to 1.76. That is too few expected variants to judge how well the gene tolerates losing a copy. Missense variants: 18 observed, 34.58 expected, observed/expected ratio (o/e) 0.52, 90% interval 0.36 to 0.77. Synonymous variants: 8 observed, 16.52 expected, observed/expected ratio (o/e) 0.48, 90% interval 0.28 to 0.87.